MTHFD2 (methylenetetrahydrofolate dehydrogenase (NADP+ dependent) 2, methenyltetrahydrofolate cyclohydrolase)
Diseases named in the same sentence as MTHFD2 in open-access papers (continued):
Sharing a sentence is not in itself a finding about the gene and the disease.
breast carcinoma (continued). "As a mechanism, the authors revealed that SIRT4 deacetylation of MTHFD2 destabilizes MTHFD2 and causes its proteasomal degradation, leading to NADPH reduction and intracellular ROS accumulation in the breast tumors which, in turn, inhibits the proliferation of the breast cancer cells." (PMID 36291902, 2022). "Secondly, highly expressed MTHFD2 is associated with poor disease outcomes in breast cancer, colorectal cancer (CRC), renal cell carcinoma (RCC), and hepatocellular carcinoma (HCC); upregulation of MTHFD2 may also contribute to an increased risk of bladder cancer." (PMID 32411609, 2020). "Interestingly, knockdown of MTHFD2 in breast cancer cells significantly affected many important metabolic pathways, suggesting that MTHFD2 might be a central metabolic enzyme in cancer cells." (PMID 32933024, 2020). "Furthermore, silencing of MTHFD2 reduced the population of CD44 cancer stem marker positive cells indicating that impairment of MTHFD2 expression reduces cancer stem cell properties in breast cancer cells." (PMID 23295955, 2013). "Moreover, MTHFD2 expression was induced in response to TGF-β stimulation in breast cancer cells." (PMID 23295955, 2013). "Moreover, our in silico gene expression analysis indicated an association with high MTHFD2 mRNA expression and characteristics of poor outcome in clinical breast cancer samples, indicating that MTHFD2 may promote disease progression." (PMID 23295955, 2013). "In our study, we explored the correlation between MTHFD2 expression levels and the TME (particularly immune cell infiltration) in breast cancer." (PMID 36726381, 2023). "We also assessed the correlation between MTHFD2 expression and immune cell infiltration in the TME of breast cancer." (PMID 36726381, 2023). "We found that in addition to being highly expressed in breast cancer (especially in TNBC), MTHFD2 modulated the proliferative, migratory, invasive, and apoptotic ability of TNBC cells." (PMID 36726381, 2023). "Then, an isozyme-selective MTHFD2 inhibitor, DS18561882, was discovered to repress the proliferation of breast cancer cell lines and the tumor growth in a mouse xenograft model with breast carcinoma upon oral administration." (PMID 35581573, 2022). "As reflected by TIMER analysis, MTHFD2 expression was considerably augmented in multiple types of cancers, like BLCA, breast cancer, cholangiocarcinoma, colon adenocarcinoma, and kidney renal clear cell carcinoma." (PMID 35581573, 2022). "MTHFD2 is a metabolic enzyme and plays an important regulatory role in tumorigenesis, including acute myeloid leukemia (AML), breast cancer, and renal cell carcinoma (RCC)." (PMID 33952272, 2021). "Collectively, these data strongly suggest that SOX7 activates SPRY1 and SLIT2, but inhibits MTHFD2 and TRIB3 in breast cancer." (PMID 29757932, 2018). "In the current study, we systematically investigated SOX7-mediated transcription in breast cancer MDA-MB-231 cells, which have an undetectable endogenous SOX7 expression, and discovered TRIB3 and MTHFD2 as its repressed genes." (PMID 29757932, 2018). "We therefore analyzed T cell cytotoxicity in kidney cancer 786-O cells, lung cancer A549 cells, breast cancer MCF-7 cells, liver cancer HepG2 cells, and colon cancer HCT-116 cells using MTHFD2 siRNA and obtained results similar to those in SW1990 cells for all these cancer cell lines." (PMID 33782411, 2021). "Despite the critical roles of MTHFD2 in breast cancer and AML, the functions of this enzyme in DLGG have not been reported." (PMID 28924174, 2017). "The results indicated that MTHFD2 depletion did not have a significant effect on cell proliferation or induction of apoptosis in these breast cancer cells." (PMID 23295955, 2013). "Furthermore, MTHFD2 expression was induced in response to TGF-&beta; stimulation in breast cancer cells." (PMID 23295955, 2013).
breast carcinoma (continued). "However, our results indicated that in highly metastatic breast cancer cells, MTHFD2 impairment did not have a significant effect on cell viability." (PMID 23295955, 2013). "The screens were done in metastatic breast cancer cells expressing vimentin at high levels and three novel vimentin regulators - WAS/WASL interacting protein family member 2 (WIPF2), methylenetetrahydrofolate dehydrogenase 2 (MTHFD2) and ephrin type-B receptor 4 (EPHB4) were identified." (PMID 23295955, 2013). "Taken together, these results indicated that in addition to vimentin, MTHFD2 depletion reduced N-cadherin expression but did not significantly modulate ZEB1, ZEB2 and SLUG transcription in MDA-MB-231(SA) breast cancer cells." (PMID 23295955, 2013).
lung carcinoma (21 papers, 2017 to 2025). "Three different studies described significant associations with patients’ survival by assessing MTHFD2 immunolabeling in 78 esophageal carcinoma samples, 323 lung cancer samples, and 137 RCC cases." (PMID 38422037, 2024). "In our study, we also observed the migration activity was impaired in MTHFD2-deficient lung cancer cells by affecting gene and protein expression of Zeb1, Vimentin and Snail." (PMID 35790743, 2022). "In addition to DNA helicases, we also observed decreased Cyclin D1 protein, a cell cycle regulator, in MTHFD2 deficient lung cancer cells." (PMID 35790743, 2022). "Lung cancer cells with acquired resistance to the targeted drug gefitinib, caused by elevated expression of components of the β-catenin pathway, exhibited increased stem-like properties and enhanced expression of MTHFD2." (PMID 30532069, 2019). "Overexpression of MTHFD2 is reported in several malignancies and associated with tumor invasion, metastasis and poor prognosis, for instance, the increased expression of MTHFD2 is correlated with tumor growth in renal cell carcinoma, hepatocellular carcinoma, and lung cancer." (PMID 35790743, 2022). "In lung cancer, MTHFD2 is activated by ATF4 to maintain redox homeostasis and contributes to cancer progression by regulating AKT/GSK-3β/β-catenin signaling." (PMID 40918462, 2025). "In lung cancer cells, MTHFD2 knockdown decreased purine nucleotides, along with an accumulation of the purine intermediate AICAR." (PMID 40604332, 2024). "In lung cancer, Moran and colleagues also reported an association between KRAS and MTHFD2 expression." (PMID 40604332, 2024). "Notwithstanding, more efforts on exploring and validating the efficacy and clinical application protocols of MTHFD2 inhibitors in lung cancer are warranted." (PMID 36138435, 2022). "High MTHFD2 expression promoted lung cancer cell proliferation and was significantly correlated with poor prognosis of NSCLC patients." (PMID 36051358, 2022). "Nevertheless, Annexin V/PI analysis by Flow cytometry and mitochondrial membrane potential detection by JC-1 staining confirmed that increased apoptosis was observed in MTHFD2 deletion lung cancer cells." (PMID 35790743, 2022). "The result showed that MTHFD2 protein level was significantly overexpressed in lung cancer cells compared with that in lung normal epithelial cell Beas‐2B." (PMID 31778025, 2020). "MTHFD2-mediated purine synthetic metabolism has been demonstrated to be critical for stem-like cell properties and resistance to chemotherapy in lung cancer cells." (PMID 32411609, 2020). "Western blotting with samples of SAECs and various lung cancer cell lines showed that MTHFD2 was expressed at varying levels among the lung cancer cell lines." (PMID 30532069, 2019). "We examined the molecular mechanisms conferring cancerous properties to MTHFD2 by performing a comprehensive analysis of the metabolome and transcriptome of H322 lung cancer cells upon MTHFD2 knockdown." (PMID 30532069, 2019). "Immunohistochemistry and western blot analysis confirmed the reduced expression of MTHFD2 in tumor tissues, indicating the critical role of MTHFD2 in cell growth and tumorigenesis in lung cancer." (PMID 30532069, 2019). "We identified MTHFD2 as a molecular target for lung cancer and showed that MTHFD2-dependent 1C metabolism is a common critical mechanism for the growth of CSCs and drug-resistant cells, as well as cancer cells in which MTHFD2 is expressed at high levels." (PMID 30532069, 2019). "Collectively, it is possible that MTHFD2-mediated 1C metabolism plays important roles for conferring drug resistance and cancer stem-like properties not only in lung cancer but also in other types of malignancy including solid tumors and leukemia." (PMID 30532069, 2019). "Examination of tissue microarrays from lung cancer patients revealed enhanced MTHFD2 expression in cancer cells compared to very low expression in normal lung tissues." (PMID 30532069, 2019).
lung carcinoma (continued). "We examined the role of MTHFD2 in A549 and H322 lung cancer cells that show high-level and moderate expression of MTHFD2, respectively." (PMID 30532069, 2019). "MTHFD2 expression analysis using TCGA data showed that MTHFD2 expression was enhanced in colorectal and lung cancers." (PMID 30582043, 2018). "We noted a significant association of SSP genes as well as SHMT2 and MTHFD2 with the expression of the asparagine synthase (ASNS), an activating transcription factor 4 (ATF4) regulated marker for amino acid and glucose deprivation in both lung cancer subtypes." (PMID 38515202, 2024). "MTHFD2 was involved in lung cancer cell proliferation, migration, and apoptosis by mediating its downstream molecules, such as DNA helicases (MCM4 and MCM7), as well as ZEB1, Vimentin and SNAI1, which contributed to tumor cell growth and epithelial-to-mesenchymal transition (EMT) process." (PMID 35790743, 2022). "In addition, another study reported that MTHFD2 sustained the properties of stem cells and gefitinib resistance in lung cancer." (PMID 36051358, 2022). "We also examined MTHFD2 protein expression in lung cancer cells and lung normal epithelial cells." (PMID 31778025, 2020). "Targeting MTHFD2 may impair the stem-like features and chemo-resistance in lung cancer, offering an opportunity for eradicating tumors and preventing recurrence." (PMID 32411609, 2020). "Therefore, we aimed to examine the metabolic functions and cellular reprograming potential of MTHFD2 in lung cancer (LCa)." (PMID 32759461, 2020). "Moreover, overexpression of MTHFD2 in gefitinib-sensitive lung cancer cells conferred resistance to gefitinib." (PMID 30532069, 2019). "Glutathione S-Transferase Omega 1 (GSTO1), Sulfotransferase Family 2B Member 1 (SULT2B1), ADH1A, ADH1B, and ADH1C were downregulated in lung cancer versus normal tissue, while ALDH3A2 and MTHFD2 were upregulated in lung cancer tissue versus normal adjacent tissue." (PMID 31717324, 2019). "EGF treatment induced MTHFD2 expression in H322, but little, if any, in A549 lung cancer cells." (PMID 30532069, 2019). "Besides, MTHFD2 was speculated as one of the regulatory targets of Nrf2, as MTHFD2 mRNA was decreased by Nrf2 knockdown in A549 lung cancer cells." (PMID 32411609, 2020). "However, the relationship between the expression of MTHFD2 and non‐small cell lung cancer (NSCLC) remains largely unknown." (PMID 31778025, 2020). "Our analysis of Kaplan–Meier plots derived from data on 1925 lung cancer patients clearly confirmed the strong oncogenic role of HK2, LDHA, PHGDH, PSAT1, SHMT2, MTHFD2, c-Myc, and ATF4 (CREB-2) in lung cancer." (PMID 37233697, 2023). "To clarify the role of MTHFD2 in lung cancer cells, we first explored the protein expression of MTHFD2 in several LUAD cell lines and detected evident MTHFD2 expression in A549, H1299 and PC9 cell lines." (PMID 35790743, 2022). "MTHFD2 knockdown (or AICAR rescue) was found to reduce stem-like properties and restore sensitivity to gefitinib in gefitinib-resistant lung cancer cells." (PMID 32411609, 2020). "Similarly, in lung cancer, ATF4 has been shown to influence MTHFD2 expression through MYC upregulation." (PMID 40604332, 2024). "Therefore, we further explored the anti-tumor effects of a MTHFD2 inhibitor, DS18561882 at 10 μM in lung cancer cells." (PMID 35790743, 2022). "TYMS expression was not related to overall survival of colorectal cancer or lung cancer patients, suggesting that MTHFD2 has a greater effect on prognosis than TYMS." (PMID 30582043, 2018). "Moreover, protein levels of RRM2 were slightly reduced in either MTHFD2 or SLC2A1 knockdown lung cancer cells, but no alteration of MTHFD1 and SLC2A1 in RRM2 knockdown cells." (PMID 33664854, 2021).
colorectal cancer (19 papers, 2018 to 2024). A primary or metastatic malignant neoplasm that affects the colon or rectum. "The knockdown of MTHFD2 in colorectal cancer reduces NADPH production and makes cancer cells more vulnerable to oxidative stress." (PMID 38794278, 2024). "Recent studies have demonstrated that overexpression of MTHFD2 was related to poor prognosis in colorectal cancer and lung adenocarcinoma." (PMID 34231329, 2021). "Knockdown of MTHFD2 in colorectal cancer hinders NADPH production and makes cancer cells more sensitive to oxidative stress." (PMID 34121323, 2021). "Overexpression of MTHFD2 predicts poor prognosis and promotes colorectal cancer cell proliferation and metastasis." (PMID 34121323, 2021). "Another study in colorectal cancer cell lines showed that knockdown of MTHFD2 suppressed cell proliferation and promoted apoptosis." (PMID 34231329, 2021). "MTHFD2 is an enzyme involved in one-carbon metabolism within the mitochondria and is upregulated in various types of solid tumors, such as lung adenocarcinoma, hepatocellular carcinoma, renal cell carcinoma, colorectal cancer, and breast cancer." (PMID 38794278, 2024). "Recently studies have shown that MTHFD2 was generally overexpressed in many kinds of malignant tumors including acute myeloid leukemia, lung carcinoma, hepatocellular carcinoma, renal cell carcinoma, colorectal cancer, and breast cancer." (PMID 34231329, 2021). "Interestingly, SIRT3 inhibition by the chemotherapeutic agent cisplatin induced acetylation of MTHFD2 (the mitochondrial methylenetetrahydrofolate dehydrogenase/cyclohydrolase) at lysine 88 (K88) and disturbed cellular redox balance in colorectal cancer cells." (PMID 34360883, 2021). "Moreover, miR‐940 and miR‐33a‐5p are reported to inhibit cancer progression through down‐regulating MTHFD2 in glioma and colorectal cancer, respectively." (PMID 34121323, 2021). "Moreover, overexpression of miR-33a-5p inhibited the migration and growth of colorectal cancer cells through the regulation of methylenetetrahydrofolate dehydrogenase 2 (MTHFD2), a mitochondrial enzyme involved in folic acid metabolism." (PMID 32505219, 2020). "Interestingly, chemotherapeutic agent cisplatin inhibits expression of SIRT3 to induce acetylation of MTHFD2 in colorectal cancer cells." (PMID 32811824, 2020). "Thus, MTHFD2 knockdown in rSCC-61 cells treated with β-lap display the G1/S arrest phenotype noted in colorectal cancer cells." (PMID 33262939, 2020). "Importantly, colorectal cancer patients with high expression of MTHFD2 had a shorter overall survival and disease-free survival than patients with low MTHFD2 expression." (PMID 30867065, 2019). "Therefore, we investigated the effect of MTHFD2 expression in each cancer patient using clinical data for colorectal cancer (GSE17536) and lung adenocarcinoma (GSE31210)." (PMID 30582043, 2018). "In addition, a clinical correlation for MTHFD2 has been reported in colorectal cancer patients." (PMID 33782411, 2021). "However, AKT was reported to regulate MTHFD2 expression via c‐Myc in colorectal cancer." (PMID 34121323, 2021). "Interestingly, we found that the acetylated K88 in MTHFD2 is dramatically decreased in tumor samples comparing with adjacent normal tissues, implying that targeting the acetylated K88 in MTHFD2 might be a potential approach for colorectal cancer treatment." (PMID 32811824, 2020). "Here, we found that SIRT3 protein levels were significantly negatively associated with acetylated K88 MTHFD2 in our colorectal tumor tissues, which suggested that inhibitors of SIRT3 or MTHFD2 might be an attractive drug to combinate with cisplatin for colorectal cancer treatment." (PMID 32811824, 2020). "In addition, MTHFD2 expression was associated with prognosis of colorectal cancer and lung adenocarcinoma; however, TYMS expression was not." (PMID 30582043, 2018).
colorectal cancer (continued). "Consistent with the knockdown data, thymidine supplementation completely rescued the viability defects in MTHFD2 inhibitor-treated HL-60 cells, a trend also observed in THP-1 AML cells and SW620 colorectal cancer cells." (PMID 35228749, 2022). "Our study suggested that MYC could bind to the promoter region of MTHFD2 and transcriptionally regulate MTHFD2 in NSCLC, consistent with previous experiments in acute myeloid leukemia and colorectal cancer." (PMID 36051358, 2022). "We also showed that acetylated MTHFD2 leads to the inhibition of NADPH production, the upregulation of the cellular ROS, which might play a vital role in the cell growth of colorectal cancer." (PMID 32811824, 2020). "MTHFD2 depletion did not significantly impact the cell cycle progression in rSCC-61 cells, consistent with findings in HeLa cells but contrary to reports showing cell cycle G1/S arrest in colorectal cancer cells." (PMID 33262939, 2020).
acute myeloid leukemia (18 papers, 2017 to 2025). Acute myeloid leukemia (AML) is a group of neoplasms arising from precursor cells committed to the myeloid cell-line differentiation. "It has previously been reported that MTHFD2 plays an important role in various tumor types such as gastric cancer, colon cancer, renal cancer, acute myeloid leukemia (AML), lung cancer, bladder cancer, and prostate cancer." (PMID 40280919, 2025). "Actually, in the scenario of acute myeloid leukemia, specific MTHFD2 inhibitors potently and selectively repress cancer cell replication while protecting non-neoplastic lymphocytes." (PMID 36138435, 2022). "Consistent with its expression profile, knockdown of MTHFD2 decreases proliferation of tumor-derived cell lines independent of tissue of origin and prolongs survival in human xenograft and mouse acute myeloid leukemia (AML) models." (PMID 35228749, 2022). "Since MYC and MAX co-occupy the LCL MTHFD2 promoter and given MYC’s role in MTHFD2 regulation in acute myelogenous leukemia, we investigated a potential role for MYC in EBV induction of MTHFD2 expression." (PMID 31257153, 2019). "Expression of MTHFD2 in tumors also correlates with poor disease outcome in breast cancer, liver cancer, and acute myeloid leukemia (AML)." (PMID 30275950, 2018). "Somewhat analogously, inhibition of the folate metabolism enzyme methylenetetrahydrofolate dehydrogenase/cyclohydrolase (MTHFD2) leads to an imbalanced dUTP:dTTP pool, increased replication stress, and preferential killing of acute myeloid leukemia (AML) cells." (PMID 39007266, 2024). "MTHFD2 inhibitors reduced replication fork speed and induced replication stress followed by S-phase arrest and apoptosis of acute myeloid leukemia cells in vitro and in vivo, with a therapeutic window spanning four orders of magnitude compared with nontumorigenic cells." (PMID 35228749, 2022). "In acute myeloid leukemia (AML), miR-92a inhibits cell proliferation and induces apoptosis by directly suppressing MTHFD2 expression." (PMID 37147729, 2023). "Inhibiting MTHFD2 with TH9619 induces thymidine depletion, suppressing acute myeloid leukemia (AML) growth." (PMID 40734168, 2025).